RNU4-42P (RNA, U4 small nuclear 42, pseudogene)
Gene: Small nuclear RNA gene on chromosome 1 (160,392,768 to 160,392,909, reverse strand). Ensembl gene ENSG00000201608.
Homologues: Orthologues: chimpanzee U4 (99% identical), macaque U4 (96% identical). Paralogues in human: RNU4-68P (87% identical), RNU4-58P (83% identical), RNU4-67P (83% identical), RNU4-7P (83% identical), RNU4-76P (82% identical), RNU4-80P (82% identical), RNU4-12P (80% identical), RNU4-13P (80% identical), RNU4-16P (80% identical), RNU4-44P (80% identical), RNU4-8P (80% identical), RNU4-84P (80% identical), and 82 more.